RNU6-250P (RNA, U6 small nuclear 250, pseudogene)
Gene: Small nuclear RNA gene on chromosome 6 (40,407,853 to 40,407,955, forward strand). Ensembl gene ENSG00000252767.
Homologues: Orthologues: chimpanzee U6 (96% identical), macaque U6 (89% identical), pig U6 (75% identical), dog U6 (74% identical), rat LOC120097304 (74% identical), rabbit U6 (65% identical), guinea pig U6 (60% identical). Paralogues in human: RNU6-812P (82% identical), RNU6-196P (81% identical), RNU6-211P (81% identical), RNU6-310P (81% identical), RNU6-966P (81% identical), RNU6-1154P (80% identical), RNU6-204P (80% identical), RNU6-768P (80% identical), RNU6-1152P (79% identical), RNU6-11P (79% identical), RNU6-37P (79% identical), RNU6-502P (79% identical), and 1286 more.